PRL (prolactin)
Diseases named in the same sentence as PRL in open-access papers (continued):
Sharing a sentence is not in itself a finding about the gene and the disease.
neuroepithelial tumors (1 paper, 2013). "A recent study by Abech and colleagues revealed presence of intracellular PRL in 45.6% of neuroepithelial tumors and meninges and elevated serum PRL in 33.9% of the cases." (PMID 23317095, 2013).
neuropathy (1 paper, 2019). A disorder affecting the nervous system that manifests with pain, tingling, numbness, and/or muscle weakness. "In agreement with previous studies in mouse models of neuropathy our data indicate that the PrL cortex undergoes functional and morphological changes already 7 days after surgery." (PMID 31263213, 2019).
obstructive hydrocephalus (1 paper, 2019). An abnormal accumulation of cerebrospinal fluid within the ventricles of the brain that occurs as a consequence of an obstruction at any location within the ventricular system that prevents cerebrospinal fluid flowing into the subarachnoid space. "The patient evolved with early improvement of clinical complaints for hydrocephalus and ICH and PRL reached normal values (11 ng/mL) in association with significant tumoral shrinkage after 18 months on cabergoline." (PMID 31555208, 2019).
Obstructive sleep apnea (1 paper, 2021). "Obstructive sleep apnea or other sleep or neurologic/psychiatric conditions could explain EDS in all participants with normal PRL." (PMID 34942875, 2021). "There are some data regarding obstructive sleep apnea (OSA), a disease that can occur with EDS and that is associated with hypoxemia and chronic sleep fragmentation, both of which could affect PRL secretion." (PMID 34942875, 2021).
oesophageal varices (1 paper, 2025). "Elevated serum prolactin levels were found in 76% of patients with oesophageal varices in this study." (PMID 39925608, 2025).
oligospermia (1 paper, 2025). Decreased number of spermatozoa in the semen. "Furthermore, both total testosterone and prolactin levels effectively distinguished severe oligospermia from healthy individuals." (PMID 40165339, 2025).
optic neuritis (1 paper, 2015). Optic neuritis is inflammation of the optic nerve, the nerve that carries the visual signal from the eye to the brain.The conditionmay cause sudden, reduced vision in the affected eye(s). "A relationship between PRL and MS relapses has been also proposed: higher serum levels of PRL were found in patients with RRMS during relapse and in patients with optic neuritis when compared to healthy controls." (PMID 26236110, 2015).
osteosarcoma (1 paper, 2022). A usually aggressive malignant bone-forming mesenchymal neoplasm, predominantly affecting adolescents and young adults. "We assessed the interaction between PRL-295 and Keap1 ectopically expressed as a fluorescently tagged protein that was genomically integrated into human osteosarcoma U2OS cells, using a modified cellular thermal shift assay (CETSA) that we developed for this purpose." (PMID 35036882, 2022).
Paget disease (1 paper, 2008). A malignant neoplasm composed of large cells with large nuclei, prominent nucleoli, and abundant pale cytoplasm (Paget cells). "Treatment with intravenous bisphosphonates improved the active Paget's disease as indicated by declining alkaline phosphatase levels and the patient's erectile function while serum prolactin levels became normal and serum testosterone levels remained unchanged." (PMID 18638386, 2008).
parasite infection (1 paper, 2013). "The opposing systemic versus thymic modulation of PRL levels during T.cruzi infection suggests that each circuitry acts independent to each other, in response tothe parasite infection." (PMID 24324845, 2013). "Although thymicatrophy was prevented in ADX infected mice and parasitemia diminished [parasites/mL(n = 5mice/day), 15 dpi: ADX group: 2500 (1000–6000), Sham group: 8000(5000–10000)], p<0.05)], circulating PRL levels remained decreased in both Shamand ADX animals." (PMID 24324845, 2013).
Parathyroid Adenomas (1 paper, 2012). "Functional effects on hormone secretion were evaluated upon prolactin stimulation of parathyroid adenoma cells." (PMID 22606260, 2012).
pemphigus vulgaris (1 paper, 2024). Pemphigus is a group of chronic autoimmune skin diseases characterized by blister formations on the outer layer of the skin and the mucous membranes. "Apart from speculation that PRL may play a role in pemphigoid gestationalis, most evidence to date has centred on the PRL and pemphigus vulgaris." (PMID 39000207, 2024).
pituitary dwarfism (1 paper, 2025). Proportionately decreased bodily growth due to failure of the pituitary gland to produce an adequate supply of growth hormone. "Patient P3, carrying the novel c.557T>G p.(Leu186Arg) variant, was diagnosed in the neonatal period with symptoms including constipation, prolonged neonatal jaundice, pituitary dwarfism, anterior pituitary hypoplasia, and low levels of IGF1, TSH, FT4, GH, and PRL." (PMID 40141050, 2025).
poisoning (1 paper, 2010). A condition or physical state produced by the ingestion, injection, inhalation of or exposure to a deleterious agent. "Case studies of patients with acute OP pesticide poisoning have also reported decreased levels of circulating thyroid hormones and increased prolactin." (PMID 20194068, 2010).
polymyositis (1 paper, 2014). A rare idiopathic inflammatory myopathy characterized by symmetric proximal muscle weakness and elevated muscle enzymes. "Herein, we describe a case of a female with a prolactin producer pituitary macroadenoma who developed severe polymyositis one month after its removal." (PMID 25431724, 2014). "In this report we describe the case of a patient with a prolactin-producing pituitary macroadenoma who, one month after its extirpation, presented with polymyositis." (PMID 25431724, 2014).
pregnancy disorder (1 paper, 2024). A disorder that is related to pregnancy. "Inability to effectively breastfeed through lack of prolactin and pregnancy disorders were other less commonly mentioned effects of hormonal imbalance on reproductive health." (PMID 39734802, 2024).
Primary amenorrhea (1 paper, 2015). "Evaluation of primary amenorrhea begins with a careful history and physical examination including the assessment of the internal and external genitalia as well as determination of FSH, thyroid stimulating hormone (TSH), and prolactin concentrations." (PMID 25785213, 2015).
ptosis (1 paper, 2022). The drooping of the upper eyelid. "Now, the tumor has remarkably shrunk in size, ptosis resolved, and the PRL level remained in a normal range." (PMID 35865778, 2022). "He underwent endoscopic transsphenoidal surgery (ETSS) based on the patient's desire (opting for surgery instead of cabergoline therapy as the first line of treatment) and cranial nerve involvement (ptosis), and 24 h post‐operation PRL was 250 ng/ml." (PMID 35865778, 2022).
renal carcinoma (1 paper, 2021). A carcinoma arising from the epithelium of the renal parenchyma or the renal pelvis. "To determine the mechanism by which prolactin promotes ccRCC, we obtained phosphorylation and transcriptome databases of 110 renal cancer patients with CPTAC and found that PRL was positively correlated with p-STAT3 (p = 0.03, rho = 0.326) and p-JAK3 (p = 0.014, rho = 0.812)." (PMID 34539753, 2021). "The study also indicated a negative feedback relationship between PRLR and PRL in renal cancer." (PMID 34539753, 2021).
renal dysfunction (1 paper, 2020). "The combination of selenium and prolactin also resulted in lower protein and urea levels (renal dysfunction markers) in the perfusates, by 65% and 74%, respectively." (PMID 32784639, 2020).
retinal ischemia (1 paper, 2019). A ischemic disease that involves the retina. "Therefore, several cell types of the GCL, INL, and PRL were investigated at six points in time after retinal ischemia." (PMID 31133806, 2019).
rosacea (1 paper, 2021). A chronic erythematous skin disorder that affects the face. "However, the levels of CRP, anti-microsomal antibody (anti-M), and prolactin were increased in rosacea patients." (PMID 34275693, 2021).
sarcoma (1 paper, 2026). A usually aggressive malignant neoplasm of the soft tissue or bone. "PRL can activate the JAK-STAT signalling pathway by binding to PRLR on sarcoma cells, leading to the up-regulation of c-MYC." (PMID 42083506, 2026). "Studies at the clinical sample, cellular and animal levels have found that abnormally elevated prolactin in the serum can originate from sarcoma tissues." (PMID 42083506, 2026).
scoliosis (1 paper, 2018). A congenital or acquired spinal deformity characterized by lateral curvature of the spine. "The degenerated NP tissues from patients had decreased expression of prolactin and its receptor, whereas expression was increased in the NP tissues removed from scoliosis patients." (PMID 29367664, 2018). "The expression of prolactin and its receptor was analyzed in human tissue obtained from symptomatic patients undergoing microencoscopy discectomy, or from scoliosis patients undergoing deformity correction surgery." (PMID 29367664, 2018).
sialorrhea (1 paper, 2023). "While on clozapine, she developed profuse sialorrhea that was treated with sublingual atropine drops, and by the time of discharge psychotic symptoms had markedly improved, perioral movements diminished, and prolactin level trended down." (PMID 38186486, 2023).
stress-related disorder (1 paper, 2023). Stress-related disorders are mental health disorders that are a result of an atypical response to both short and long-term anxiety due to physical, mental, or emotional stress. "Stress is a contributor to many disorders, especially neuropsychiatric disorders; therefore, this review will primarily focus on the role of PRL as a potential target in stress-related disorders and the consequences that arise when PRL dysregulation is the cause of such disorders." (PMID 36833950, 2023).
tendinopathies (1 paper, 2023). "The available scientific data confirmed that metabolic changes caused by relaxin and prolactin hormonal disorders could induce tendinopathies affecting both tendon and ligament structures during pregnancy." (PMID 37180059, 2023).
testicular cancer (1 paper, 2017). A primary or metastatic malignant neoplasm that affects the testis. "Other authors also suggest that hCG concentrations in testicular cancer patients correlate with testosterone, prolactin, estradiol and gonadotropins concentrations." (PMID 28389909, 2017).
testicular tumors (1 paper, 2017). "In our material, prolactin concentrations also changed significantly over time; this leads to a conclusion that prolactin balance is disrupted in patients with testicular tumors." (PMID 28389909, 2017).
toxocariasis (1 paper, 2018). A parasitic infection caused by worms found in domestic animals. "During toxocariasis, there is no clear evidence indicating that PRL or other hormones, are essential in the development of the infection, as it has been reported for other parasites." (PMID 29921576, 2018).
tumor syndrome (1 paper, 2022). "Although in macroprolactinomas we found a normalization of prolactin level in 43 patients within an average of one year, the tumor syndrome disappeared in 31.6% of cases." (PMID 36540468, 2022).
uremia (1 paper, 2019). A clinical syndrome associated with the retention of renal waste products or uremic toxins in the blood. "Both uremia and prolactin negatively affect gonadal function by inhibiting the secretion of gonadotropin-releasing hormone and luteinizing hormone for testosterone production in the Leydig cells." (PMID 31351493, 2019). "The possible mechanisms for the association between impaired kidney function and low testosterone levels are multi-factorial including uremia and increased prolactin levels." (PMID 31351493, 2019).
uterine cancer (1 paper, 2020). Primary or metastatic malignant neoplasm involving the uterine corpus and/or the cervix. "Therefore, PRL and PRL-Rs appear to play an important role for the activation of signaling pathways involved in uterine cancers and preneoplastic lesions." (PMID 33162942, 2020).
uterine diseases (1 paper, 2020). "PRL is implicated in the pathogenesis of malignant, premalignant and benign uterine diseases: it directly impacts cervical and endometrial tumorigenesis and promotes cell proliferation in uterine myomatosis." (PMID 33162942, 2020).
uterine infection (1 paper, 2022). "The top three upstream regulators predicted to be activated in the endometrium of pregnant cows after uterine infection include 1) IFNG (cytokine); 2) IFNA2 (cytokine); and 3) PRL (cytokine)." (PMID 35358206, 2022).
uterine neoplasms (1 paper, 2020). "UTROSCTs are rare uterine neoplasms with literature citing less than 80 cases in total, with only one case associated with ectopic prolactin." (PMID 32857272, 2020).
vitamin C deficiency (1 paper, 2025). "Additionally, studies on Gulo-/- mice have shown that vitamin C deficiency affects the amount of hydroxyproline in the skin and the prolactin-stimulated mammary gland." (PMID 41228556, 2025).
tumor (612 papers, 1973 to 2026). "This suggests that excessive PRL (and the underlying tumor) impacts the growth axis, likely through central growth hormone or thyroid hormone deficiency." (PMID 40599499, 2025). "Remission rate was associated with lower baseline prolactin levels, early tumor shrinkage, and initial transsphenoidal surgery." (PMID 41199869, 2025). "Some clinical characteristics such as old age, extrasellar tumor extension with relatively low prolactin levels, visual defects, and growth hormone (GH) deficiency favor NFPAs." (PMID 40960781, 2025). "PRL also elevates reactive oxygen species (ROS) and boosts phagocytic and cytotoxic capacity in tumor‐associated macrophages." (PMID 41476991, 2025). "Remarkably, this catalytic C-to-D mutation preserves PRL oncogenicity in a cellular model of tumor implantation." (PMID 40398601, 2025). "The PRL/CNNM complex is linked to tumor progression through the accumulation of intracellular magnesium." (PMID 38904264, 2024). "In the macroadenoma group significant association was found only between preoperative serum PRL level and tumor size (r = 0.412, p < 0.016)." (PMID 38375408, 2024). "Prior data have shown that hormone remission rates following surgery are closely associated with tumor size, preoperative PRL levels, invasion, and resistance to DAs." (PMID 38398117, 2024). "Prepregnancy duration of dopamine agonist treatment (particularly for longer than 1 year), small tumors, and lower prolactin levels before pregnancy reduce the risk of tumor growth and increase the chance of tumor regression after pregnancy and lactation." (PMID 38578473, 2024). "Sometimes, supra normal prolactin levels associated with persistent tumor mass are even desired, in an attempt to prevent a breach at the level of the sellar floor, fragilized by the tumor." (PMID 39109291, 2024). "This suppressive effect is likely exacerbated by the higher PRL levels typically associated with larger tumor size." (PMID 39337013, 2024). "This study has several strengths, including a large sample size, pre-diagnosis measures of prolactin, and associated tumor tissue." (PMID 36882838, 2023). "Further, larger studies are needed to assess joint associations of biologically relevant tumor markers including of other prolactin-related pathways." (PMID 36882838, 2023). "Giant prolactinomas account for approximately 2% to 4% of all prolactinomas, are characterized by significant extrasellar extension, and are usually defined as a maximum tumor diameter of ≥40 mm in association with prolactin (PRL) >1000 μg/L." (PMID 37403202, 2023). "It encodes a co-chaperone protein, which acts as a tumor suppressor, especially versus GH and PRL PitNETs." (PMID 37958702, 2023). "The treatment goals for a prolactinoma include the normalization of prolactin levels and associated signs and symptoms, along with complete tumor removal or shrinkage and a reversal of the tumor mass effects." (PMID 36835974, 2023). "In patients with prolactinomas, there is a correlation between PRL levels and tumor size at diagnosis, an association that seems less evident in giant prolactinomas (r = 0.24-0.63)." (PMID 37403202, 2023). "The treatment, either DA or surgery, should lower PRL levels to allow conception and in case of MP should shrink tumor within sellar limits in order to minimize the risk of enlargement during pregnancy." (PMID 35000899, 2022). "These tumors can develop without postpubertal ovarian steroids, similar to the observation that the increased risk conferred by PRL in women is independent from estrogen, although supplemental 17β-estradiol decreases tumor latency." (PMID 35784527, 2022). "Increased prolactin levels have also been linked to the higher invasiveness of specific tumor types." (PMID 35625802, 2022). "In the case of PRL tumors, most tumors contained more than two dominant alleles in each of the three target genes, suggesting that the analyzed tumor nodules originated from more than a single cell." (PMID 36192757, 2022).